CRP (C-reactive protein)
Diseases named in the same sentence as CRP in open-access papers (continued):
Sharing a sentence is not in itself a finding about the gene and the disease.
depression (continued). "For instance, in a longitudinal study, higher levels of IL‐6 in childhood, but not CRP, were associated with increased risk of depression and psychosis in young adulthood (Khandaker, Pearson, Zammit, Lewis, & Jones, 2014)." (PMID 36597271, 2023). "These markers include CRP and IL-6; the study concluded that depression and anxiety in RA patients were driven by the same immune-inflammatory pathway which is part of the pathophysiology of RA disease itself, and not driven by the experience and burden of the disease." (PMID 37346903, 2023). "Fourth, regarding the concurrent correlation, we found that depression was not concurrently associated with CRP levels in 2011 (r = −0.01, p = 0.36)." (PMID 36860788, 2023). "Significant associations were observed between CRP, depression, and physical activity (ps < 0.05), but not between inflammation and other symptoms." (PMID 37444517, 2023). "We aim to investigate inflammation, proxied by C-reactive protein (CRP) levels, and body mass index (BMI) as putative causal risk factors for depression and subsequent treatment resistance, leveraging genetic information to avoid confounding via Mendelian randomisation (MR)." (PMID 37710313, 2023). "Elevated levels of inflammatory factors such as C-reactive protein (CRP) and interleukin 6 (IL-6) may promote the development of depression." (PMID 37032915, 2023). "Previous research has indicated that depression is accompanied by increased levels of inflammatory markers, such as C-reactive protein (CRP) and interleukin-6, which could be particularly relevant for treatment-resistant depression." (PMID 37904091, 2023). "Several reports indicated that patients with depressive disorders have higher levels of pro-inflammatory cytokines, such as C-reactive protein (CRP), interleukin (IL)-1, (IL)-6, and tumor necrosis factor-alpha (TNF-alpha) in their plasma than healthy individuals." (PMID 37916205, 2023). "Our results do not show a deniable association between immune system activity and MDD, thus, it is plausible that other inflammatory profiles, besides CRP, IL-6 and TNF, may be associated with different depression subtypes." (PMID 36966195, 2023). "Among the PA mutation carriers, we documented different numbers of cases across all the conditions, ranging from 1 (0.3% for celiac disease) to 33 (10.6% for depressive disorder) for the CRP gene and 1 (0.2% for psoriatic arthritis) to 68 (10.3% for depressive disorder) for the G6PC gene." (PMID 37493001, 2023). "CRP levels, SNPs, and isomers may assist in guiding treatment selection for patients diagnosed with a depressive disorder." (PMID 37181328, 2023). "Further studies are needed in order to better understand the core mechanism through which CRP may interact in depression and which role CRP may have in characterizing subgroups of depressed patients and guide treatment strategies." (PMID 35163538, 2022). "The discrepancies observed within the sensitivity analyses using continuous CRP as an exposure and continuous depression and anxiety as outcomes suggest that the way the variables are handled may influence the observed associations." (PMID 36198766, 2022). "Further genetic and immunological investigation is necessary to determine whether CRP, IL-6, NFL, or other inflammatory cytokines may have a causal relationship with depression." (PMID 35618889, 2022). "Similarly, our previous review has demonstrated that depression and anxiety are associated with elevated TNF-α, IL-6, IFN-α, and C-Reactive Protein (CRP) levels." (PMID 35053845, 2022). "In the smoking-CRP, smoking-IL-6 activity, smoking-depression, and depression-smoking analyses, all of the global estimates calculated using robust MR methods, excluding the MR-Egger estimate, showed a similar increase in the odds of the outcome and higher levels of the exposure." (PMID 36057695, 2022).
depression (continued). "For instance, an earlier study in patients with treatment-resistant depression showed that the tumor necrosis factor antagonist infliximab reduced depressive symptoms to a greater extent than placebo when baseline CRP levels were above 5 mg/L compared to when CRP levels were below this threshold." (PMID 35566447, 2022). "Similarly, patients with depression and anxiety have upregulated CRP levels in comparison to controls." (PMID 35053845, 2022). "Larger studies allowing for extensive adjustment of correlates of CRP post-MI may further substantiate an independent relationship between lifetime depression and persistently elevated CRP levels post-MI." (PMID 35566447, 2022). "Taken together, these findings suggest that CRP may be a trait marker, while neutrophil and eosinophil counts are likely to be state markers of current depression." (PMID 35379263, 2022). "Omega-3 fatty acids are protective against depression in older men by decreasing C-reactive protein (CRP) levels, while the total intake of fat, saturated fatty acids (SFA), and monounsaturated fatty acids (MUFA) exerted an increased effect on both CRP and interleukin (IL)-6 in older women." (PMID 36615742, 2022). "Second, neither depression nor fatigue was associated with microbiome alpha diversity or inflammatory activity as determined by serum CRP or faecal calprotectin levels." (PMID 36244970, 2022). "Among non-leukocytic components of circulating inflammation, CRP explained 4.6% of the associations between depression severity and IHD events (p = 0.048)." (PMID 36311535, 2022). "The current study found that CRP levels were not related to the severity of anxiety and depression but were significantly associated with BMI." (PMID 36313504, 2022). "Endothelial dysfunction, elevated C-reactive protein (CRP), platelet dysfunction, and reduced flow-mediated vascular dilation leading to accelerated atherosclerotic plaque formation in CAD patients are linked with depression." (PMID 36237772, 2022). "CRP was reported to be a marker of depression with a predictive value of progression to dementia." (PMID 35326481, 2022). "In addition, venlafaxine has been reported to play an anti-inflammatory role through downregulation of serum TNF-α, IL-1β, IL-6, and CRP in major depressive disorder and animal researches." (PMID 35664492, 2022). "Moreover, the neurovegetative depression cluster displayed significantly elevated CRP levels compared to other clusters." (PMID 35361785, 2022). "However, our results were consistent with previous research showing that IL-6 more consistently predicts stress levels and depression than CRP." (PMID 35873737, 2022). "We assessed differential blood counts, CRP, depression symptoms (HAMD-21) and psychosocial functioning (GAF) in controls (n = 129) and patients with first (FEMD: n = 82) or recurrent (RMD: n = 47) disease episodes of MD at baseline (T0; hospital admission) and after 6-weeks treatment (T6)." (PMID 35379263, 2022). "A cross-sectional study exploring whether CRP SNPs were related to depressive symptoms and antidepressants efficacy assessed 440 patients with first-episode depression through HAMD-17, finding gender-specific SNP differences." (PMID 35163538, 2022). "CRP levels also correlate with treatment-resistant depression, which could explain why patients with RA are more susceptible and less responsive to antidepressant therapy." (PMID 36422176, 2022). "Two new associations in Wave 2 data included a negative association between alcohol and depression in females, and a negative association between CRP and cardiovascular risk in males." (PMID 35895279, 2022). "We tested the associations of ACEs, hair cortisol, C-reactive protein (CRP), and polygenic scores (PGS) with depression, anxiety, and loneliness among older adults during the COVID-19 pandemic, accounting for the potential interplay of ACEs with biological and genetic risk markers." (PMID 36198766, 2022).
depression (continued). "Importantly, both Niles’ and Deverts’ groups note that their findings with CRP were mostly driven by somatic symptoms of depression." (PMID 35617264, 2022). "Nevertheless, the association between high CRP (i.e., ≥3 mg/L) and depression was no longer significant after the analyses were adjusted for confounders." (PMID 35163538, 2022). "The size of the effect, however, varied significantly between studies, this could be due to clinical heterogeneity, as severe depression has a higher CRP than mild/moderate depression, as well as differences in study methodology." (PMID 36217471, 2022). "Our results did not confirm that the association of the DII and depression is mediated by the body’s immune function associated with CRP." (PMID 35565951, 2022). "However, more than one-third (38.6%) of the unipolar depression patients displayed high CRP levels (i.e., >3 mg/L)." (PMID 35163538, 2022). "Higher CRP levels were observed in atypical MDD with respect to the typical manifestation, and were associated with reduced quality of life and late-onset depression." (PMID 35163538, 2022). "In patients with or without history of heart disease, depression is also associated with elevated cytokine levels (especially CRP, IL-1, and IL-6)." (PMID 36248418, 2022). "Indeed, in a cumulative meta-analysis in adult patients with clinical depression, conducted on 58 observational studies, it was concluded that IL-6, CRP, and TNF-α were more strongly associated with severe depression than with moderate depression." (PMID 35360574, 2022). "These discrepancies may be due to the current study having a smaller sample size and a larger time gap between the CRP and depression assessments." (PMID 36198766, 2022). "Specific inherited CRP SNPs (A allele in rs1417938 and C allele in rs1205) may be responsible for up-regulating serum CRP levels and thus bated with depression occurrence." (PMID 35163538, 2022). "Moreover, CRP levels were higher among men who had a recent episode of depression and who had recurrent depression." (PMID 35163538, 2022). "The factors associated with cognitive decline in patients with JIA were average C-reactive protein (OR [95% CI], 1.377 [1.060–1.921]; p = 0.039), depression (OR [95% CI], 3.691 [1.294–10.534]; p = 0.015), and treatment with biologics (OR [95% CI], 0.188 [0.039–0.998]; p = 0.046)." (PMID 35885032, 2022). "Interestingly, patients with major depressive disorder exhibit increased peripheral blood concentrations of CRP, and elevated CRP levels predict resistance to standard antidepressant therapies." (PMID 35432388, 2022). "Circulating CRP levels have also been associated with increased depression scores in an elderly non-demented population." (PMID 35643540, 2022). "Patients with a positive family depression history had higher CRP blood levels." (PMID 35163538, 2022). "One prospective study on young individuals did indicate that depression episodes increased CRP levels and as such may be considered an inflammatory promoter." (PMID 35330865, 2022). "The link between inflammation with increased concentrations of C-reactive protein, ferritin, and interleukin-6; with depression might also explain some of the psychiatric morbidity." (PMID 36040960, 2022). "Evidence from a longitudinal twin-study suggests that different inflammatory cytokines might interact with depression differently: elevations in CRP may perhaps be a consequence of depression, while elevations in IL-6 act as a risk factor for depression." (PMID 35618889, 2022). "Patients with depression who have a high level of CRP are also more likely to have treatment-resistant depression, suggesting that there is a subset of patients who may show additional benefit with adjunctive therapy." (PMID 35370812, 2022). "Subjects who displayed persistently elevated CRP levels also had increased ORs of moderate/severe depression at 18 years, even though this association was not statistically significant." (PMID 35163538, 2022).
depression (continued). "It is speculated that CRP may serve as a useful marker of inflammation in the antidepressant treatment of depression." (PMID 35722555, 2022). "Our study was not designed to examine direct pathophysiological mechanisms that might link a history of depression with CRP levels in patients with acute MI." (PMID 35566447, 2022). "It is an intriguing assumption that based on this literature patients with a history of depression and elevated CRP post-MI might particularly benefit from, for instance, anti-interleukin-1 treatment in terms of better cardiovascular outcome." (PMID 35566447, 2022). "Also, serum CRP is used as an inflammatory biomarker, and a high CRP level is related to depression and euthymia." (PMID 36232200, 2022). "The existing literature on air pollution studies indicates that air pollution can lead to systemic inflammation and elevated CRP, and systemic inflammation has emerged in the literature as one of the plausible biological mechanisms in the pathogenesis of depression and PTSD." (PMID 35886474, 2022). "Similarly, elevated IL-10 and CRP levels are associated with PTSD and depression in chronic mTBI population." (PMID 35053845, 2022). "While a major portion of this study is focused on depression, we also wanted to investigate the relationship between CRP and other psychiatric phenotypes such as anxiety and substance use given previous reports linking anxiety and substance use with inflammation." (PMID 35821205, 2022). "There is a study that analyzed whether CRP and TG were related to suicide attempts in patients with major depressive disorder." (PMID 35418704, 2022). "Low-grade inflammatory response, defined as an elevation in serum interleukins and CRP, could have a role in depression etiology and may be an effective indicator of active treatment." (PMID 36160713, 2022). "As expected, all mediation effects of CRP in the associations between ACEs and depression were almost null and nonsignificant." (PMID 35241782, 2022). "BMI is especially important because studies have shown a small association between CRP and depression when BMI is adjusted, but studies not adjusting for BMI have shown an effect size three times as large." (PMID 35821205, 2022). "Among these inflammatory biomarkers, numerous studies focused on depression and CRP." (PMID 35163538, 2022). "Indeed, there is evidence that CRP levels show less variability in individuals with depression and that IL-6, IL-8 and TNF-α levels show less variability in individuals with psychotic disorders." (PMID 36085284, 2022). "The study is aimed at evaluating the immune-activation state before and after treatment in patients with first-episode depressive disorder (FDD) with evaluating the ILs and CRP levels and further clarifying the association between autoimmunity and the etiology and pathogenesis of FDD." (PMID 35615531, 2022). "Furthermore, several studies investigated the role of a set of specific inflammatory biomarkers in depressive disorders, including C-Reactive Protein (CRP)." (PMID 35163538, 2022). "Both CRP elevation and GE were entered as independent variables in two further general linear models in order to exploratory illustrate the interaction between peripheral and central inflammation markers in the context of depression in newly diagnosed MS." (PMID 34764926, 2021). "That this association was present for only SDS-depressed participants argues either for consideration of a vulnerability-to-depression effect for the association between overall CM and CRP, or for the existence of the CM-CRP link to be an outcome of depression." (PMID 34867491, 2021). "Consequently, this study assumed that certain pro-inflammatory pathways that promote increased CRP levels would disturb the integrity of the amygdala–prefrontal cortex circuit and add to the persistence of depression." (PMID 34943627, 2021).
depression (continued). "In contrast to studies reporting on an association of depression and CRP levels, several studies also found that hsCRP was not elevated during depressive episodes in general or during episodes of prenatal maternal depression." (PMID 34360212, 2021). "Interestingly, earlier and recent large-scale genomic studies found that the genetic overlap between BMI, CRP and leptin with depression is symptom specific; this overlap was only found in depressed patients with increased hypersomnia, weight and appetite." (PMID 34078486, 2021). "The prevalence of low-grade inflammation (CRP > 3 mg/L) in depression is 27%." (PMID 33672126, 2021). "Higher IL-6 and CRP can predict the development of depression." (PMID 34054732, 2021). "Our results indicate that it may be due to increased trans-signalling, because we also see that SNPs in the CRP gene that increase CRP levels are protective for depression." (PMID 34505025, 2021). "However, other studies have reported that the concentrations of IL-1β, IL-6 and/or CRP in the serum or cerebrospinal fluid were positively correlated with depression severity only, or more profoundly in females." (PMID 33672958, 2021). "However, meta-analytic surveys of existing evidence have concluded that links between CRP concentration and future depression in both adults and children are weak and inconsistent." (PMID 34887380, 2021). "A total of 91 records were displayed using various combinations of the following search terms: CRP, major depressive disorder, SSRI, SNRI, ketamine, antidepressants, sertraline, escitalopram, citalopram, mianserin, trazodone, agomelatine, venlafaxine, duloxetine." (PMID 33920992, 2021). "Depression score was positively related to the levels of CRP in a linear manner." (PMID 34421539, 2021). "Importantly, these differences are linked to epigenetic alterations, as blood cells from individuals with a lifetime history of depression show alterations to DNA methylation in IL-6 and CRP." (PMID 34924946, 2021). "Univariate logistic regression models, where depression status was the dependent variable, showed statistically significant associations with fibrinogen, IL-6, CRP and the generalised inflammation factor, but not with TNF-α." (PMID 33064180, 2021). "We observed 4 gut microbiome PRS interacting with CRP were associated with both PHQ-9 score and GAD-7 score in our study, which may be related to the pathophysiology of anxiety and depression through the communication of peripheral inflammation to the brain." (PMID 34481527, 2021). "Also, baseline CRP levels (>621.6 ng/mL) have been suggested to differentiate between bipolar and unipolar depression." (PMID 33946871, 2021). "People with symptoms of depression or anxiety frequently have an increased level of CRP." (PMID 34481527, 2021). "At a multiple regression analysis, the 25(OH)D concentration was the only significant predictor of CRP and depression, so that for each 1.0 nmol/L decrease in serum levels of 25(OH)D, there was an increase by 0.041 mg/L in serum levels of CRP and an increase by 0.063 points in depression score." (PMID 33670644, 2021). "In addition, compared with participants without fatigue, participants with fatigue and low-grade inflammation as measured by CRP were shown to have mental health problems, including psychological distress, depression, and sleep problems." (PMID 34774052, 2021). "Concerning hsCRP itself, the literature suggests that the inflammatory response represented by CRP can be helpful identifying subgroups of depressed patients (e.g., atypical vs. typical depression), but is less suitable for characterizing general depression." (PMID 33733300, 2021). "Thus, proinflammatory cytokines and molecules such as TNF-α, IL-6, interleukin 1 (IL-1), soluble interleukin 2-receptor (sIL-2R), and C-reactive protein (CRP) measured in serum are increased in patients with depression as compared to healthy subjects." (PMID 34764926, 2021).